GSDME (gasdermin E)
Diseases named in the same sentence as GSDME in open-access papers (continued):
Sharing a sentence is not in itself a finding about the gene and the disease.
tumor (continued). "Instead, targeting GSDME as a tumor promoter may be a more promising strategy." (PMID 40544161, 2025). "Finally, this study observed that erianin induces GSDME-dependent pyroptosis in ATC tumor cells, suggesting it may enhance antitumor immunity by releasing immunostimulatory molecules." (PMID 40978473, 2025). "Finally, etoposide 43 exerts its pyroptotic effects on various tumor cells by activating GSDME." (PMID 39316325, 2025). "Therefore, we believe that GSDME might have enormous potential to act as new tumor marker and biotherapeutic target for HCC." (PMID 38434972, 2024). "Therefore, specifically inducing pyroptosis by upregulating GSDME expression in tumor cells may be a promising antitumor strategy." (PMID 38643134, 2024). "When GSDME is activated in tumors, it can transform “cold” tumors that are not recognized by the immune system into “hot” tumors that can be regulated by T cells and tumor-killing cells in the immune system; tumor growth is inhibited and cancer patients benefit from immunotherapy." (PMID 39526199, 2024). "Therefore, regulation of protein expression through methylation modification may be an important regulatory mechanism involved in tumor occurrence by GSDME." (PMID 38169676, 2024). "The increased expression of GSDME in tumor cells may make it more sensitive to chemotherapy." (PMID 38902235, 2024). "Consequently, selectively trigger GSDME-mediated pyroptotic tumor cell death could enhance tumor immunogenicity and avoid immune attacks and side effects." (PMID 38104141, 2023). "GSDME expression in HNSCC tumour tissue is upregulated and may be a biomarker for poor prognosis." (PMID 36600313, 2023). "Consequently, ADC therapy may induce GSDME-mediated pyroptotic cell death in GSDME-expressing cells, thereby regulating anti-tumor immunity and therapeutic response." (PMID 38104141, 2023). "Unlike GSDMD, several studies have implicated GSDME as a tumor suppressor." (PMID 37077542, 2023). "Interestingly, particularly GSDME seems to act as a tumor suppressor." (PMID 37771587, 2023). "The expression of GSDME could sensitize radio‐resistant tumor cells to radiation in human CRC." (PMID 37125240, 2023). "Besides GSDMD, GSDME also plays different roles in tumor development." (PMID 37313458, 2023). "Mechanistically, GSDME-mediated pyroptosis is synergically driven by chemo-photodynamic therapy and controlled-release paclitaxel, releasing DAMPs and triggering immune responses, which plays an anti-tumor role and generate immunological memory to prevent tumor recurrence." (PMID 35462927, 2022). "As a tumor suppressor, GSDME may slow down tumor growth and invasion." (PMID 34553845, 2022). "Additionally, GSDME methylation status lead to the lower GSDME expression in some tumor cell types, compared with that in normal tissues, which makes it difficult for most tumor cells to activate the pyroptosis." (PMID 35321945, 2022). "Interestingly, the robust pyroptosis induction observed in vitro seems not to directly affect tumor development in vivo, as GSDME deficiency or GSDMB overexpression failed to alter tumor growth." (PMID 36077828, 2022). "Above, these findings demonstrated that GSDME might function as a tumor suppressor." (PMID 35462927, 2022). "Myricetin could promote the high expression of cleaved-GSDME in tumor tissues." (PMID 36091790, 2022). "At the same time, high GSDME expression was found in RB vascular endothelial cells in paraffin sections of human RB tissues, and for tumor treatment, whether tumor cell death can be further promoted by inducing pyroptosis of vascular endothelial cells will be our next research direction." (PMID 35480866, 2022). "Therefore, in the envisioned strategy, Adriouch team aims to use viral vectors, akin to AAV, to induce ICD intratumorally by expressing active truncated/mutated forms of GSDMD, GSDME or MLKL, thus bypassing tumor resistance to the induction of pyroptosis or necroptosis." (PMID 35883457, 2022).
tumor (continued). "Furthermore, IHC displayed higher GSDME protein levels in OTUD4-overexpressing tumor xenografts." (PMID 36411454, 2022). "Based on this, researchers found that DNA methyltransferase inhibitors could inhibit the hypermethylation of the GSDME promoter region in tumor cells with a low GSDME expression, thereby increasing the expression of GSDME in tumor cells and inducing pyroptosis." (PMID 36612023, 2022). "Therefore, promoting GSDME palmitoylation is a promising target for tumor therapy." (PMID 35462927, 2022). "Recently, it has been reported that two members of the GSDM family, namely GSDMD and GSDME, stimulate numerous downstream pyroptotic pathways, and the downregulation of these molecules conversely contributed to tumorigenesis and proliferation in the tumor cell microenvironment." (PMID 36003332, 2022). "It was also confirmed that GSDME-mediated pyroptosis could promote T-cell recruitment through the release of relevant cytokines and trigger the activation of T cells to stimulate T-cell infiltration into tumor tissues." (PMID 35847844, 2022). "Additionally, to further determine whether GA-induced pyroptosis is involved in the reduction in tumor volume, the expression of GSDME was evaluated." (PMID 36428598, 2022). "In addition, our TGCA analysis of HNSCC samples showed that GSDME overexpression in tumor compared to normal tissue, correlates with worse OS, which may be explained by the reported lack of tumor infiltrated lymphocytes in GSDME+ HNSCC tumors by other authors." (PMID 35120582, 2022). "Thus, the activation of pyroptosis driven by GSDME may be an important manner to eliminate tumor resistance." (PMID 35462927, 2022). "This indicates that GSDME may have an inhibitory effect on tumor growth." (PMID 34553845, 2022). "Thus, activating caspase-3/GSDME-dependent pyroptosis specifically in CXCR4+ HNSCC tumor cells may represent a novel and enticing approach for the treatment of HNSCC patients." (PMID 35120582, 2022). "Thus, GSDME is considered to have a tumour-suppressing function." (PMID 35292781, 2022). "Further study found that the number of tumor-infiltrating CD3+ T cells was enhanced when increased GSDME expression and the levels of chemokines that recruit T-cells after DDP treatment, indicating that GSDME may induce T-cell activation in mediating T-cell infiltration into tumor tissue." (PMID 36523974, 2022). "Tumor cells undergoing pyroptosis could release gasdermin E and inflammatory factors to boost the infiltration of both tumor-suppressed immune cells such as CD8+ T cells and NK cells as well as tumor-promoting cells like myeloid-derived suppressor cells (MDSCs)." (PMID 35242763, 2022). "Additionally, CAR T cell‐released GzmB triggers GSDME‐mediated pyroptosis in target tumour cells." (PMID 34590363, 2021). "Thus, further research is needed to investigate whether GSDME-dependent pyroptosis is involved in the DDP-induced anti-tumor effect of TNBC." (PMID 34326697, 2021). "In this study, our result showed that GSDME may play a tumor promoting role in HCC." (PMID 34925465, 2021). "This implies that GSDME-induced pyroptosis is, in principle, not linked to the liberation of IL-1β and may thereby be associated with improved anti-tumor effects." (PMID 34490126, 2021). "All of this suggests that GSDME might be a tumor suppressor and worth in‐depth exploration." (PMID 34459122, 2021). "Finally, a role for GSDME as a potential tumor marker has also been proposed." (PMID 35111698, 2021). "Furthermore, chemotherapy drugs can activate GSDME, a tumor candidate, to promote pyroptosis." (PMID 34123855, 2021). "Also, DAC can demethylate the GSDME gene in tumor cells with specific tumor‐bearing mice." (PMID 34459122, 2021). "When the expression of GSDME was low in tumor cells, the DNA methyltransferase inhibitor decitabine could inhibit the hypermethylation of its gene promoter, thus leading to pyroptosis of tumor cells." (PMID 33840390, 2021).
tumor (continued). "Thus, GSDME-mediated tumor suppression was attributed to cytotoxic lymphocyte killing." (PMID 33634141, 2021). "Moreover, CAP provided a kind of local treatment without systemic side effects and might be employed as a more promising tumor treatment via inducing GSDME-mediated pyroptosis." (PMID 32341339, 2020). "Moreover, the expression of GSDME determines the death mechanism of tumor cells." (PMID 33133646, 2020). "Next, we harvested tumor tissues and stained them with eEF2K, GSDMD, and GSDME immunofluorescence markers." (PMID 40567376, 2025). "Despite both GSDME and GSDMB being triggered by killer cells, GSDME appears to have stronger tumor-suppressive properties." (PMID 41291696, 2025). "This tumor suppressive function of GSDME was attributed to increased phagocytosis of tumor cells by macrophages and increased infiltration of natural killer cells and CD8+ tumor cells, contributing to anti-tumor immunity." (PMID 40544161, 2025). "Collectively, our study demonstrates that erianin exerts potent anti-tumor activity in ATC by simultaneously inhibiting the MAPK/ERK and PI3K/Akt signaling pathways, thereby inducing apoptosis and GSDME-dependent pyroptosis." (PMID 40978473, 2025). "Immunohistochemical analysis reveals a strikingly high positivity rate for GSDME in approximately 78% (289/371) of HCC specimens, far exceeding the 12% (6/50) positivity rate in adjacent non-tumor tissues." (PMID 40568597, 2025). "Hydralazine upregulated the expression of GSDME, and the released mitoxantrone (MIT) induced the activation of caspase, leading to pyroptosis of tumor cells." (PMID 40698137, 2025). "Artenimol 60 is a sesquiterpene that displayed an anticancer activity against NSCLC with pyroptotic induction via GSDME activation, while euxanthone 61 has pyroptotic activity on HCC tumor cells by activating caspase-2." (PMID 39316325, 2025). "As a result of promoter methylation of the DFNA5 gene, the expression of GSDME in most mouse tumor cells is far lower than normal cells." (PMID 39816682, 2025). "In vivo, LHA significantly reduced tumor growth and altered tumor histopathology in a PDAC xenograft model, along with downregulated eEF2K and upregulated pyroptosis executors (GSDMD/GSDME)." (PMID 40567376, 2025). "Together with statistical analysis of necrotic tumor areas, these findings indicated that 2-DG inhibited tumor growth by activating cAMP/PKA pathway, thereby suppressing HK2 expression and promoting GSDME-mediated pyroptosis." (PMID 41415273, 2025). "Mechanistic studies revealed that HMB exerted its synergistic anticancer effects by triggering GSDME‐dependent pyroptosis in CRC cells, organoids and various mouse tumor models." (PMID 39950759, 2025). "In recent years, there has been an increasing number of reports on PDT-inducing pyroptosis in tumor cells, broadly categorized into two main pathways: through GSDMD and GSDME." (PMID 40169560, 2025). "As a DNMT inhibitor, RG108 can effectively inhibit DNA methylation and reactivate the GSDME gene, which can be cleaved by Caspase‐3 induced by CDDP, then triggers the pyroptosis in tumor cells and produces immunotherapeutic effects." (PMID 40432601, 2025). "Based on the results of our investigation, GSDME had positive effects for migration of the activated-CD8+T cells by IFNβ, which suggested IFNβ played a key role in anti-tumor immunity." (PMID 38853246, 2024). "The expression levels of GSDMB and GSDME were higher in tumor grades 2 and 3 compared to normal tissues, whereas GSDMA expression level was significantly increased in tumor grade 2 compared to normal tissues." (PMID 39607202, 2024). "Tumor cells can be perforate by PFN secreted by lymphocytes and GZMB can enter the cytoplasm and cleave GSDME to release its N-GSDME to induce pyroptosis." (PMID 38853246, 2024). "Gasdermin E (GSDME, also called DFNA5) was recently identified as another pyroptotic “executioner” and suppresses tumor growth by activating anti-tumor immunity." (PMID 38799433, 2024).
tumor (continued). "Elevated expression of GSDME enhances the RT sensitivity of CRC and increases tumor immune infiltration." (PMID 39062587, 2024). "More recently, Alisol A, a marine herb with anti-tumor effects, was found to induce pyroptosis by increasing the levels of caspase-1, GSDMD, and GSDME in CRC cells, while reducing cancer cell migration and increasing the chemosensitivity of cisplatin." (PMID 39062587, 2024). "Overall, these observations demonstrated that REGγ inhibition promoted pyroptosis through the indirect regulation of GSDME and GSDMD in both macrophages and tumor cells." (PMID 39349939, 2024). "In vivo, okanin reduced tumor growth and involved pyroptosis-related markers such as CASP1, GSDMC, GSDMD, and GSDME." (PMID 39335166, 2024). "Hence, multiple tumor cells could enhance immune escape by reducing the expression of GSDME." (PMID 38238307, 2024). "The expression of GSDME leads to NK cells and CD8+ T cells infiltrate the tumor more frequently and functioning better, as well as TAMs phagocytose more effectively." (PMID 37752941, 2023). "Tetraarsenic hexoxide (As4O6) could increase mitochondrial ROS generation by preventing STAT3 phosphorylation, causing caspase 3/GSDME‐dependent pyroptotic cell death and ultimately inhibiting tumor proliferation and metastasis in triple‐negative breast cancer cells." (PMID 37752941, 2023). "GSDME‐mediated pyroptosis accelerates the progression of CAC by releasing HMGB1, which stimulates tumor cell proliferation and PCNA expression via the ERK1/2 pathway." (PMID 37752941, 2023). "GSDME (also known as ICERE1 or DFNA5), which is present in both tumor cells and normal tissues, has the ability to convert caspase-3-mediated apoptosis to pyroptosis upon exposure to chemotherapy agents." (PMID 38104141, 2023). "To gain further insight into the role of CDC20 in anti-tumor immunity, and we generated multiple TRAMP-C2 cell lines with various independent shRNAs constructs targeting CDC20 or GSDME." (PMID 37528490, 2023). "GSDME has been shown to enhance the phagocytosis of macrophages, as well as the number and function of NK cells and CD8(+) T lymphocytes, thereby exerting tumor inhibition." (PMID 37221570, 2023). "Collectively, the data confirmed that oncolytic ORFV-elevated GSDME plays a critical role in the process of ORFV-reshaped tumor immune microenvironment and ORFV-induced tumor suppression in immunologically “cold” tumors." (PMID 36641456, 2023). "Compared with normal tissues, BAK1 and GSDME levels were markedly elevated in HCC tumor tissues, meanwhile, the expression of the NLRP6 showed the opposite trend as decreasing in HCC tumor samples in contrast with normal samples." (PMID 37149620, 2023). "Previous reports have shown that when GZMA cleaved GSDMB or GZMB cleaved GSDME, NK cells and CD8(+) T cells directly triggered pyroptosis of tumor cells." (PMID 37221570, 2023). "H&E and TUNEL staining indicated that GSDME overexpression combined with SIM induced more intensive DNA fragmentation and ultimately cell death in the tumour, accompanied by decreased Ki67 expression, a cell proliferation marker." (PMID 35517821, 2022). "Gasdermin B (GSDMB) and Gasdermin E (GSDME) are cleaved by Granzymes A and B, respectively, into their active pore-forming subunits inducing death of tumour cells by pyroptosis and resulting in local inflammation." (PMID 35626754, 2022). "The phosphorylation of GSDMA Thr8, corresponding to GSDME Thr6, is attributed to the PKL1 kinase activation, which possibly counteracts the function of GSDME as a tumor suppressor." (PMID 35462927, 2022).
tumor (continued). "GSDME-mediated cell scorch death promotes colorectal cancer progression by releasing HMGB1, which induces tumor cell proliferation and PCNA expression through the extracellular regulated protein kinases 1/2 (ERK1/2) pathway." (PMID 35958626, 2022). "In vitro and in vivo assays were used to investigate the function of gasdermin E (GSDME) and ovarian tumor family deubiquitinase 4 (OTUD4)." (PMID 36411454, 2022). "When granzymes were delivered directly to tumor cells during a cytotoxic T cell attack, GSDMB and GSDME were cleaved into N- and C- terminal fragments by GZmA and GZmB, respectively." (PMID 36159393, 2022). "It was shown that HMGB1 induces proliferation of tumor cell and expression of PCNA through ERK1/2 pathway to promote the occurrence of IBD-related CRC, while GSDME-mediated pyroptosis can release HMGB1." (PMID 36092900, 2022). "Gasdermin E (GSDME) is one of the important proteins that mediate cellular pyroptosis and has been found to act as a tumour suppressor by activating tumour pyroptosis, thereby enhancing the antitumour immune effect." (PMID 35812396, 2022). "Interestingly, a large percent of HNSCC patients could be candidates to targeted nanotoxin therapy since in our 17-patient cohort, 88.2% were positive for the CXCR4 receptor, 94% of them expressed GSDME in tumor tissue, whereas 87% of GSDME+ tumors also co-expressed CXCR4." (PMID 35120582, 2022). "Immunohistochemistry (IHC) was used to evaluate the differential expression of major PRGs (GSDMC, GSDMD, GSDME, NLRP3, NLRC4, IL1B) in selected tumor types (COAD, HNSC, KIRC, LIHC, LUAD, LUSC)." (PMID 36605187, 2022). "Both GSDMD and GSDME have been focused in the field of tumor-targeted therapy, and several small molecule agents or nano-drugs targeting GSDMD and GSDME have been developed." (PMID 35739593, 2022). "GSDME-mediated pyroptosis of epithelial cells enhance the progression of CRC by releasing HMGB1, which promotes tumour proliferation by activating the ERK1/2 signalling pathway." (PMID 35896522, 2022). "As for the tumor grade, GSDMD and GSDME expression increased gradually and significantly from grade 1 to grade 4." (PMID 34731088, 2021). "The chemotherapeutic drug cisplatin regulates the release of immune factors in the induction of GSDME-mediated pyroptosis, and the level of MIP-1α, MIP-1β, MIP-2 and IP-10 in tumor tissues and blood are increase." (PMID 34381721, 2021). "Additionally, GSDME upregulation inhibits tumor proliferation as well as colony forming ability, and reduces the incidence of lymphatic metastasis, demonstrating that GSDME may act as a tumor suppressor." (PMID 34335940, 2021). "Consistently, increased cleavage of caspase 3, PARP, and GSDME was detected in CBD treated HCC cells and tumor sections." (PMID 34350183, 2021). "GSDME-mediated pyroptosis promotes the development of CAC by releasing HMGB1, which induces tumor cell proliferation and PCNA expression through the ERK1/2 pathway." (PMID 33160389, 2020). "When the tumor was irradiated, pyroptosis was induced by activated caspase-1 cleavage of GSDME, which significantly increased the production of ROS, and the levels of TNF-α and IFN-γ were significantly elevated, promoting the death of tumor cells by T cells and other killer immune cells." (PMID 40698137, 2025). "We demonstrate that GSDME has tumor-promoting functions independent of pyroptosis, including suppression of T cell infiltration and invasion of GB cells." (PMID 40544161, 2025). "Furthermore, knockdown of CypD, the target protein of DHN, greatly impaired the suppressive effect of DHN on tumor growth as well as STING polymerization and GSDME cleavage, emphasizing the requirement of CypD for the DHN effect." (PMID 40663398, 2025). "In vivo, upregulation of GSDME increased HCC sensitivity to Lenvatinib and inhibited tumor growth." (PMID 40653759, 2025).